TRIP13 (thyroid hormone receptor interactor 13)
Diseases named in the same sentence as TRIP13 in open-access papers (continued):
Sharing a sentence is not in itself a finding about the gene and the disease.
gastric cancer (6 papers, 2020 to 2025). A primary or metastatic malignant neoplasm involving the stomach. "Background/Objectives: Gastric cancer (GC), a prevalent global malignancy and a leading cause of cancer-related mortality, has a poorly understood prognosis related to TRIP13 expression." (PMID 41007830, 2025). "In combination, these results indicate that TRIP13 is abnormally activated in gastric cancer and is significantly associated with poor prognosis in gastric cancer patients." (PMID 39187490, 2024). "The results revealed that overexpression of DDX21 after knocking down TRIP13 rescued the proliferation restrain of gastric cancer cells caused by knocking down TRIP13." (PMID 39187490, 2024). "The results indicate that the expression of rescue TRIP13 significantly restores the proliferation inhibition of gastric cancer cells caused by knocking down TRIP13." (PMID 39187490, 2024). "Other integrated analyses have identified EXO 1, DTL, KIF 14, and TRIP13 as significant genes that could serve as potential diagnostic biomarkers related to gastric cancer." (PMID 40445003, 2025). "Knocking down TRIP13 and rescuing its expression could restore the inhibition of gastric cancer cell migration and invasion caused by knocking down TRIP13." (PMID 39187490, 2024). "Finally, microarray analysis of TRIP13-related pathways was performed to identify the potential underlying mechanism of TRIP13 in gastric cancer." (PMID 37432513, 2023). "The flat panel clone formation assay, Edu assay, and transwell experiment revealed that knocking down the expression of HDAC1 and overexpressing TRIP13 could rescue the inhibition of proliferation, migration, and invasion ability of gastric cancer cells caused by knocking down HDAC1." (PMID 39187490, 2024). "These experimental results reveal that DDX21, as a binding protein of TRIP13, promotes the development of gastric cancer through its interaction with TRIP13." (PMID 39187490, 2024). "The results validate that TRIP13 was highly expressed in gastric cancer tissue samples, and the expression of TRIP13 increased with the increase of gastric cancer grade." (PMID 39187490, 2024). "The expression of TRIP13 was analysed through the TCGA data set, to determine the function of TRIP13 in gastric cancer." (PMID 39187490, 2024). "Existing studies have revealed that TRIP13 is highly expressed in gastric cancer and participates in the proliferation and apoptosis of gastric cancer cells." (PMID 39187490, 2024). "The Edu assay and plate clone formation assay revealed that knocking down TRIP13 significantly repressed the proliferation of gastric cancer cells." (PMID 39187490, 2024). "The results indicate that high expression of TRIP13 results in poor prognoses for gastric cancer patients." (PMID 39187490, 2024). "Overall, this study confirms that TRIP13 is involved in the proliferation, migration, invasion in vitro and tumourigenesis and metastasis in vivo of gastric cancer cells." (PMID 39187490, 2024). "In gastric cancer cells knockdown TRIP13, knockdown of TRIP13 significantly restrains the growth of gastric cancer cells." (PMID 39187490, 2024). "This study confirms that TRIP13 is highly expressed in gastric cancer tissue samples and that TRIP13 participates in the proliferation, migration, invasion in vitro, and tumourigenesis and metastasis in vivo of gastric cancer cells." (PMID 39187490, 2024). "KEGG enrichment analysis in transcriptomics shows significant enrichment in the PI3K/AKT signaling pathway and gastric cancer after knocking down TRIP13." (PMID 39187490, 2024). "Subsequently, the expression of TRIP13 was detected in normal gastric mucosal tissue and gastric cancer tissue samples of different grades through immunohistochemistry experiments." (PMID 39187490, 2024). "Database analysis demonstrates that TRIP13 is highly expressed in gastric cancer and various other tumours." (PMID 39187490, 2024).
gastric cancer (continued). "The cell scratch assay and transwell assay revealed that knocking down TRIP13 significantly reduced gastric cancer cell migration and invasion ability." (PMID 39187490, 2024). "The MTT and flat clone formation assays were adopted to detect the effect of overexpression of DDX21 after knocking down TRIP13 on the proliferation ability of gastric cancer cells." (PMID 39187490, 2024). "The current study demonstrates that TRIP13 is abnormally activated in gastric cancer, and the immunohistochemistry assay reveals that as the grade of gastric cancer increases, the expression of TRIP13 also increases." (PMID 39187490, 2024). "Mass spectrometry analysis was undertaken further to investigate the molecular mechanisms of TRIP13 in gastric cancer." (PMID 39187490, 2024). "The current study confirms that TRIP13 is highly expressed in gastric cancer and participates in the proliferation, tumourigenesis and metastasis of gastric cancer cells." (PMID 39187490, 2024). "Depletion of TRIP13 in gastric cancer cells reduces proliferation, tumour growth, and tumour metastasis, inducing a cell cycle arrest, which is rescued by the reconstituted expression of TRIP13." (PMID 39187490, 2024). "A stable gastric cancer cell line knocking down TRIP13 using lentiviral interference technology was developed to explore the effect of TRIP13 on the proliferation ability of gastric cancer cells." (PMID 39187490, 2024). "The RNA sequence data were retrieved from TCGA to evaluate TRIP13 mRNA expression in gastric cancer." (PMID 37432513, 2023). "In our study, bioinformatics analysis of the TCGA database revealed that TRIP13 has been overexpressed in the cancer cells from the stomach compared with the normal gastric cells, confirming that TRIP13 is an oncogene for gastric cancer." (PMID 37432513, 2023). "In conclusion, TRIP13 participates in the carcinogenesis of stomach cancer, and its overexpression in the cancerous tissues from gastric malignancy dovetail with advanced stage and survival." (PMID 37432513, 2023). "Although previous studies have suggested that the overexpression of TRIP13 carries the prognostic potential to predict the development of gastric cancer, there have been very few studies on its mechanism." (PMID 37432513, 2023). "MTT assays demonstrated that TRIP13 knockdown tuned down gastric cancer cell proliferation (P < 0.05)." (PMID 37432513, 2023). "Immunohistochemical analyses of malignant and adjacent normal samples in the cancerous stomach also showed overexpression of TRIP13 in gastric cancer cells." (PMID 37432513, 2023). "In conclusion, TRIP13 participates in the carcinogenesis of stomach cancer, and its overexpression in the cancerous tissues dovetail with advanced stage and survival." (PMID 37432513, 2023). "Additionally, analysis of the UALCAN and ENCORI databases reveals that TRIP13 is highly expressed in gastric cancer." (PMID 39187490, 2024). "Next, the prognosis of TRIP13 in gastric cancer was analysed using the Kaplan–Meier plotter." (PMID 39187490, 2024). "Overall, this study reveals the reasons for the abnormal activation of TRIP13 in gastric cancer, inferring that TRIP13 might become a biomarker for early diagnosis of gastric cancer." (PMID 39187490, 2024). "Finally, a tail vein injection experiment in mice was undertaken to evaluate the effect of TRIP13 on the in vivo metastasis ability of gastric cancer cells in mice." (PMID 39187490, 2024). "Substantially, these results reveal that DDX21 plays the oncogene role in gastric cancer and TRIP13 could restrain the ubiquitination degradation of DDX21." (PMID 39187490, 2024). "Moreover, the use of de novo protein synthesis inhibitor cycloheximide (CHX) to detect the DDX21 turnover rate demonstrated that the DDX21 degradation rate was slowed down in gastric cancer cells overexpressing TRIP13." (PMID 39187490, 2024). "We found that DDX21 protein expression was reduced in TRIP13 knocked-down gastric cancer cells." (PMID 39187490, 2024).
gastric cancer (continued). "In contrast, the number and size of lung nodules in mice that rescued TRIP13 expression were significantly larger than in mice that knocked down TRIP13, demonstrating that TRIP13 might promote metastasis of gastric cancer via triggering the EMT process." (PMID 39187490, 2024). "We aimed to explore the biological effect of TRIP13 on gastric cancer." (PMID 37432513, 2023). "Additionally, the small molecule inhibitor DCZ0415 targeting TRIP13 could repress the proliferation of gastric cancer cells through plate cloning and Edu assays." (PMID 39187490, 2024). "Our research results indicated that TRIP13 is in an abnormally activated state in gastric cancer, and patients with high expression of TRIP13 have poor prognosis, revealing that TRIP13 might play an essential role in the tumour development process of gastric cancer." (PMID 39187490, 2024). "However, the molecular mechanisms by which TRIP13 participates in gastric cancer proliferation, tumourigenesis and metastasis remain unclear." (PMID 39187490, 2024). "Additionally, histone deacetylase 1 (HDAC1) is an upstream factor of TRIP13, which could target the TRIP13 promoter region to promote the proliferation, migration, and invasion of gastric cancer cells." (PMID 39187490, 2024). "However, the biological function and molecular mechanism of TRIP13 in gastric cancer remain unclear." (PMID 39187490, 2024). "Mechanically, the current study confirms that TRIP13 interacts with DDX21, and mediates the inhibition of ubiquitination degradation of the latter, thereby facilitating the progression of gastric cancer." (PMID 39187490, 2024). "Further research revealed that TRIP13 interacted with DDX21 and is significantly positively correlated in gastric cancer tissue samples." (PMID 39187490, 2024). "The experimental results identify a significant positive correlation between TRIP13 and DDX21 in gastric cancer tissue samples." (PMID 39187490, 2024). "An immunohistochemical assay was adopted to investigate the expression of TRIP13 and DDX21 in the same gastric cancer tissue samples." (PMID 39187490, 2024). "Mechanistically, this study confirms that TRIP13 directly interacts with DDX21 and stabilises its expression by restraining its ubiquitination degradation, thereby promoting gastric cancer progression." (PMID 39187490, 2024). "Finally, TRIP13 was found to restrain the ubiquitination degradation of DDX21, promoting the progression of gastric cancer." (PMID 39187490, 2024). "For these reasons, our results suggest that FPR2, CARD14, CXCR2, EFNA2, CXCR1, AQP9 TRIP13, along with GHRL and KLK11, could be used as promising biomarkers for gastric cancer diagnosis or prognostic evaluation." (PMID 34012923, 2021).
lung adenocarcinoma (6 papers, 2015 to 2025). A carcinoma that arises from the lung and is characterized by the presence of malignant glandular epithelial cells. "TRIP13 also promoted lung adenocarcinoma cell proliferation, clonogenicity, and migration while inhibiting apoptosis and G2/M phase transition in vitro." (PMID 36268276, 2022). "The genes CEP72, BRD9, TRIP13, SLC9A3, SDHA, SLC6A19 and PDCD6 did not have any predictive role in lung adenocarcinoma prognosis." (PMID 26497366, 2015).
Wilms tumor (5 papers, 2018 to 2024). An embryonal neoplasm characterized by the presence of epithelial, mesenchymal, and blastema components. "Humans with biallelic mutations in TRIP13 are highly susceptible to Wilms tumor and chromosome missegregation due to impairment of the spindle assembly checkpoint." (PMID 38216586, 2024). "Previous observations in patient-derived lymphoblasts from a patient with Wilms tumor which harbor a loss of function mutation in TRIP13 have reported a decrease in proliferation upon TRIP13 overexpression." (PMID 38589567, 2024). "Taken together, we have identified that KPT-330 acts in part by inhibiting TRIP13 in Favorable Histology Wilms Tumor." (PMID 38589567, 2024). "A functional genomics approach in patient derived cell lines of Favorable Histology Wilms Tumor identifies suppression of TRIP13 through the nuclear export inhibitor, KPT-330, leads to decreased viability and synergy with doxorubicin." (PMID 38589567, 2024). "Tumor predisposition has been observed in patients with biallelic LoF of BUB1B, TRIP13, and MAD1L1, with resulting elevated risks for rhabdomyosarcoma, Wilms tumor, and a variety of malignancies, respectively." (PMID 37796616, 2023).
B-cell lymphoma (4 papers, 2017 to 2025). "Hence, TRIP13 expression detection in a wide range of B-cell lymphoma including Diffuse Large B Cell Lymphoma, Mantle Cell Lymphoma and Mucosa-associated Lymphoid Tissue Lymphoma is also meaningful." (PMID 28424416, 2017). "The qPCR data of TRIP13 expression level in cell lines showed that not only CLL lines but also B-cell lymphoma cell lines had high TRIP13 mRNA level, which indicated that TRIP13 may be a broad-spectrum oncogene in B-cell lymphoma." (PMID 28424416, 2017). "Interestingly, TRIP13 (thyroid hormone receptor interactor 13) characterized by DepMap as Strongly Selective was critical for the maintenance of several cancer cell lines including B-cell lymphoma OCILY19 and Human eosinophilic leukemia EOL1." (PMID 38464090, 2024). "This analysis revealed that TRIP13 was expressed in T-cell lymphoma (T8ML-1, MJ, HH), T-cell leukemia (JURKAT, MOLT4, MOT, SUPT1, LOUCY, CCRF-CEM, DND-41) B-cell lymphoma (RAJI), B-cell leukemia (MEC-1, MEC-2) and myeloid leukemia (K562, CTV-1) cell lines." (PMID 38464090, 2024).
epithelial ovarian cancer (4 papers, 2020 to 2026). "TRIP13 is identified as a potential oncogenic gene in ovarian cancer." (PMID 41907269, 2026). "Finally, a group investigated the role of the thyroid hormone receptor Interactor 13 (TRIP13) in epithelial ovarian cancer (EOC)." (PMID 32533406, 2020). "This investigation highlighted CCNA2, TRIP13, CDK1, CDC20 and PRC1 as viable targets for our structure-based drug discovery campaign, as they all had a crystallised structure available in the Protein Data Bank, strong evidence of a role in ovarian cancer and known inhibitors." (PMID 39184376, 2024).
female infertility (4 papers, 2022 to 2024). Diminished or absent ability of a female to achieve conception. "Homozygous and compound heterozygous missense variants in TRIP13 are associated with female infertility, characterized by oocyte meiotic arrest and abnormal zygotic cleavage." (PMID 39684710, 2024). "Specific recessive pathogenic variants of TRIP13 that impair mitosis and meiosis have been linked to distinct diseases, including Wilms tumors and female infertility." (PMID 39684710, 2024). "In summary, our study expanded the mutation and phenotype spectrum of TRIP13 and suggested that human TRIP13 biallelic variants can cause cell cycle progress abnormalities that result in female infertility characterized by human ZCF." (PMID 35812326, 2022). "Different types of TRIP13 recessive pathogenic variants cause distinct diseases, including Wilms tumors and female infertility through the different effects on mitosis and meiosis." (PMID 36360157, 2022). "Homozygous and compound-heterozygous pathogenic TRIP13 missense variants are associated with female infertility, mostly characterized by oocyte meiotic arrest and abnormal zygote cleavage." (PMID 36360157, 2022). "Female mice lacking TRIP13 display a severely impaired ovarian reserve, and biallelic pathogenic variants of TRIP13 reportedly cause OMA and female infertility." (PMID 35812326, 2022).
Infertility (4 papers, 2017 to 2025). "The clinical effect, infertility, of the homozygous TRIP13 missense variant described here, is obviously limited to meiosis." (PMID 40702521, 2025). "Thus, the present study, in relation to the individual previous studies, aims to identify SPA17, PPP1R36, AURKA, TRIP13, PLK4, CCDC90B, and CCDC91 genes as important biomarkers of both teratozoospermia- and azoospermia-associated infertility in men." (PMID 36292606, 2022). "Thus, Pch2/Trip13 is an important regulator of meiotic processes, and mutation of the TRIP13 gene causes infertility in humans." (PMID 33712914, 2021).